CD4 (CD4 molecule)
Diseases named in the same sentence as CD4 in open-access papers (continued):
Sharing a sentence is not in itself a finding about the gene and the disease.
tumor (continued). "Quantitative analyses using digital pathology showed a significant positive correlation between high VISTA expression and intratumoral CD3+, CD4+Treg, and CD8+ infiltration, while PD-L1 expression in tumor cells correlated specifically with CD3+ and CD8+ infiltration within tumor nests." (PMID 41562715, 2026). "First, we analyzed CD4+ and CD8+ T-cell infiltration into the tumor microenvironment." (PMID 41431358, 2026). "Although combination therapy with [211At]1 and αCTLA-4 enhanced therapeutic efficacy, αCTLA-4 did not induce tumor infiltration of CD4+ or CD8+ T cells." (PMID 40768094, 2026). "We observed specific T cell activation, determined by cytokine secretion and expression of activation markers in both CD4+ and CD8+ T cells, and induction of T cell-mediated cytotoxicity in co-cultures when TCEs with specificity for targets expressed on the tumor cells were produced." (PMID 41552759, 2026). "To investigate the long-term functional capacity of iPSC-derived CD4+ and CD8+ T cells—and to assess whether their combination enhances therapeutic efficacy—we employed a multi-round tumor challenge assay." (PMID 41484912, 2026). "Additional IHC staining for CD8+, CD4+, and FOXP3 + T cells demonstrated immune cell infiltration into mouse tumor that received 4‐1BBL/IL‐12 nanoparticles, and little immune cell infiltration into mouse tumor that received luciferase nanoparticles." (PMID 41496905, 2026). "The tumor microenvironment was immunosuppressive, with reduced infiltration of CD4 + and CD8 + T cells and B cells, and lacked classical Treg/Tex populations." (PMID 41761191, 2026). "Through targeted T cell depletion experiments, we established that CD8+ T cells are indispensable for the vaccine's anti-tumor activity, whereas CD4+ T cell depletion had no significant impact on therapeutic outcomes." (PMID 42079630, 2026). "Furthermore, AKK can promote the recruitment and infiltration of CD4+ T cells into the TME, enhance immune surveillance functions, and inhibit tumor cell immune escape mechanisms, ultimately improving the clinical efficacy of PD‐1 blockade immunotherapy." (PMID 41574027, 2026). "Here, we show that genetically deleting the epigenetic factor DNA methyltransferase 1 (Dnmt1) in endothelial cells (ECs) reduces angiogenesis while imparting profound changes to the tumor immune microenvironment (TIME), including increased proportions of CD4+ memory T cells and NK cells." (PMID 42156591, 2026). "This contribution to tumor resistance likely did not come from CD4 T cells as Bcl6fl/fl OX40-cre mice showed tumor growth curves comparable to Bcl6fl/fl controls." (PMID 41145211, 2026). "The exclusion of CD4 and CD8 T cells at the tumor periphery might suggest reduced immune surveillance and anti-tumor responses, and increased immunosuppression in the context of fatty liver." (PMID 41545340, 2026). "In contrast, CD4+ T cells promote tumor growth in B16F10-mock tumors but do not affect the growth of B16F10-ULBP2 tumors." (PMID 40243581, 2025). "From the fundamental view, it is important that peptide vaccine efficiency targeted at CD4+ cells does not rely on tumor inflation of activated Th cells." (PMID 40650228, 2025). "The distribution of lymphoid populations formed a gradient ranging from stroma-restricted lymphoid aggregates composed of both CD3+CD4+ and CD3+CD8+ T cells to single CD3+CD8+ T cells that had penetrated NOS2+/– edges and into the tumor satellite and core regions." (PMID 40663402, 2025). "Moreover, Tregs, a subset of CD4+ T cells, are the primary targets of anti-CTLA-4 for anti-tumor efficacy." (PMID 40861801, 2025). "As noted in Introduction, stimulation of the TNFR superfamily members OX40 and 4-1BB has been shown to increase Tem cell responses to viral and tumor antigens, including increased IFN-γ production by both CD4+ and CD8+ T cells following vaccination of mice against poxvirus." (PMID 40178907, 2025).
tumor (continued). "Moreover, after CB‐AKK treatment, a significant number of activated T lymphocytes (CD4+ T and CD8+ T) were produced in the spleen and tumor cells of the mice." (PMID 40497373, 2025). "Seventeen CD4+ TCR clonotypes were experimentally validated by reconstructing TCRs in healthy donor T cells and testing their reactivity to patient-specific neoantigens via coculture assays with antigen-presenting cells and autologous tumor material." (PMID 40634636, 2025). "Immune alterations also include increased CD4 +/CD8 + and IL-17 + γδ T cells, and elevated expression of immunosuppressive (IDO1, IL-10, PD-L1) and oncogenic (AKT1, STAT3, CXCR4) genes with key roles in tumor progression and immune evasion." (PMID 40924302, 2025). "A negative correlation between the density of tumor-infiltrated CD4+CXCL13+ cells pre-NAIC and %RVT (spearman’s r = − 0.6412, p = 0.0002) was observed, and this correlation was more pronounced in post-NAIC (spearman’s r = − 0.7691, p < 0.0001)." (PMID 40295492, 2025). "On the other hand, Tregs are FOXP3- and CD25-positive CD4+ T lymphocytes (CD4+CD25+FoxP3+) that promote immunosuppression and a tolerogenic tumor microenvironment by secreting inhibitory cytokines such as TGF-β and IL-10 and by interacting with other immune cells." (PMID 40805183, 2025). "The data does, however, indicate that any pro-tumorigenic effect of Tregs following Apc deletion in the ISC is unlikely to be due to their role in suppressing anti-tumour CD4+ or CD8+ T-cells." (PMID 39877864, 2025). "In addition, treatment with hCD38-mAtt resulted in an increased number of NK cells, as well as CD4 T cells and CD8 T cells in the tumor, compared with controls." (PMID 40315226, 2025). "Phases 1 and 2 data support this hypothesis showing LI augmentation of CD4+ T (and others) cell infiltrates and CD4/CD8 ratio in the tumor and tumor microenvironment (TME)." (PMID 40191245, 2025). "Moreover, TGFBR2 inhibition reverses this immunosuppressive tumor cell phenotype by reducing CD8+ T cell exhaustion and enhancing CD4+ and CD8+ T cell-mediated tumor cell killing." (PMID 40277917, 2025). "T cells, including differentiated CD4+ helper T cells and CD8+ cytotoxic T cells, elicit an anti-tumor effect in the TME by directly killing cancer cells in an antigen-specific manner and combating tumor growth through the release of cytokines." (PMID 40508074, 2025). "To investigate whether there was a spatial correlation between infiltrated immune cells and tumor vessels, we also stained CD31+ endothelial cells and measured the distance from CD4+ and CD8+ T cells to tumor vessels." (PMID 39967849, 2025). "Additionally, VV that drives IL-9 gene expression demonstrated prolonged viral persistence in tumors and increased CD4+ and CD8+ T-cell infiltration in the tumor microenvironment in mice." (PMID 40867310, 2025). "Recent scRNA-seq studies on T-cells within PDAC patients have reported T-cell marker genes in CD8+ Tcm, CD4+ Tem, and γδT cells, and noted that the CCL5/SDC1 receptor–ligand interactions in tumor-infiltrating T-cells could promote tumor cell migration." (PMID 40906153, 2025). "Additionally, TACE has been associated with increased infiltration of immune cells, such as CD3, CD4, and CD8 T-lymphocytes into the tumor, as well as higher expression of immune checkpoint markers, such as PD-1 and PD-L1." (PMID 40002242, 2025). "CD68 expression has significant negative relation with tumor purity, significant positive correlation with tumor-infiltrating levels of B cell, CD4+ T cell, CD8+ T cell, macrophage, myeloid dendritic cell and cancer associated fibroblast in STAD." (PMID 40918116, 2025). "Regarding the differences in the tumor microenvironment (TME) between the two subtypes, we observed that C2 was rich in the infiltration of several immune cells, such as Activated CD4 T cell, Central memory CD4 T cell, Effector memory CD4 T cell, T follicular helper cell, Type 1 T helper cell, etc.." (PMID 40599775, 2025).
tumor (continued). "An enhanced expression of TIGIT on tumor-infiltrating CD8+ and CD4+ T cells in HNSCC patients was correlated with CD8+ functional exhaustion and impaired activation and proliferation as well as with the expression with other immune checkpoint molecules such as PD-1." (PMID 40650111, 2025). "Results indicate that Xcl1-E6E7+mIL-9 maintained its function following CD4+ T cell depletion but failed to prevent tumor development after CD8+ T cell depletion." (PMID 39852828, 2025). "Therefore, we simultaneously stained CD4+ and CD8+ T cells and CD206+ M2 TAMs in the syngeneic tumor tissues using multiplex Immunofluorescence (mIF)." (PMID 41306557, 2025). "Additionally, consideration should be given to including both CD4+ and CD8+ T cell epitopes to synergistically promote anti-tumor immunity." (PMID 41567982, 2025). "Notably, LAG-3 is frequently co-expressed with PD-1 on CD4+ and CD8+ tumor-infiltrating T cells, and their combined blockade has shown enhanced immunotherapeutic efficacy." (PMID 40723175, 2025). "RNA deconvolution analysis of the tumour microenvironment further demonstrates reduced adaptive immune responses and decreased immunogenicity, with lower infiltration of immune-promoting macrophages, effector CD8+ T cells, and CD4+ T cells." (PMID 41295253, 2025). "The strategy was effective in vitro and co-culture of human peripheral blood mononuclear cells (PBMC) and LGR5+ NALM6 (pre-B ALL) tumour cells in the presence of α-LGR5 bispecific led not only to robust CD4+ and CD8+ T-cell activation but also potent and specific tumour cell killing." (PMID 40405910, 2025). "Indomethacin treatment also increased CD4+ T cells; however, these cells did not infiltrate the tumor but remained at the tumor margin." (PMID 40663402, 2025). "Moreover, while both CD4+ and CD8+ T cells contribute to anti-tumor immunity, the balance between these two cell types is crucial for maintaining effective immune function." (PMID 40308586, 2025). "However, T cells exhibited a significant higher expression of PD-1 (mean on CD4+: 17% ± 12 SD; mean on CD8+: 27% ± 19 SD) on tumor infiltrating lymphocytes (TIL) compared to healthy donors or patient blood (CD4+ = p = 0.004; CD8+ = p = 0.002)." (PMID 40860824, 2025). "The results suggested that depletion of CD8+ T cells weakened the inhibitory effect of Dtx2 knockdown on tumor growth, while depletion of CD4+ T cells had no such effect." (PMID 39733452, 2025). "Since CD4+ and CD8+ T lymphocytes are critical for cytotoxic antitumor immune responses, their depletion may compromise immune surveillance and promote tumor proliferation, invasion, and metastasis." (PMID 41568363, 2025). "CD4+ and CD8+ T cells can recognize and eliminate tumor cells presenting the specific antigen." (PMID 40145100, 2025). "In addition, γδT cells were subdivided according to CD4 and CD8 expression pattern, whereby a CD4+ phenotype was more abundant in ascites and tumor samples, with > 50% of γδT cells each." (PMID 41221283, 2025). "In addition to the influence of CD4-positive T-cells, we analyzed a possible influence of cytotoxic T-cells (CD8+) and macrophages in the tumor area." (PMID 40975763, 2025). "Distances of total CD8+ T-cells (27.1 vs 33.6 μm; p = 0.098), total CD4+ T-cells (31.2 vs 35.5 μm; p = 0.225) and Tregs (30.1 vs 40.6 μm; p = 0.383) to a tumour cell were not statistically different between HPV-negative and HPV-positive OAC." (PMID 41310655, 2025). "Notably, a significant rise of CD3+CD4+ T cell cluster and CD3+CD8+ T cell cluster was presented in the TM@CD326hOMV groups compared to the untreated tumor, demonstrating the reprogramming of the immune desert toward an immune‐inflamed phenotype." (PMID 40270472, 2025). "Notably, local activation of MCMV-specific CD4+ T cells led to immune activation in the TME and promoted epitope spreading against tumor-specific antigens." (PMID 40280970, 2025).
tumor (continued). "For instance, tumor cells with high HLA-II expression (e.g., KYSE270) may more effectively activate CD4+ T cells, enhancing immune responses against neoantigens and thereby improving the patient’s immune status." (PMID 40940814, 2025). "No relevant correlations were observed for the tumor periphery, but CD4 T cell frequencies increased with TG 54:3 in kidney tissues." (PMID 40902455, 2025). "We mixed CD4 and CD8 CAR T cells at a 1:1 ratio prior to coculture with target cells and observed a notable increase in the frequency of CD8+ of the CARCD28ζ T cells as early as 24 hours of coculture with tumor cells." (PMID 39792660, 2025). "On the immune side, 5-HT1A receptors expressed on T cells promote the expansion of CD4(+)CD25(+)Foxp3(+) regulatory T cells while lowering the Th1/Th2 ratio, whereas on tumor cells, 5-HT1A receptor activity negatively correlates with cytotoxic lymphocyte function." (PMID 41007799, 2025). "These chemokines are key signaling molecules that recruit CD4+ T cells and CD8+ T cells to the tumor immune microenvironment; reduced expression of these chemokines leads to insufficient infiltration of anti-tumor immune cells, further weakening immune surveillance." (PMID 41409294, 2025). "The plasticity of CD4+ T cells is also notable; mature CD4+ T cells can adopt a cytotoxic phenotype under certain conditions, exhibiting MHC-II-restricted cytotoxicity, which is essential for their direct role in killing tumor cells." (PMID 40177538, 2025). "The primary components of TILs are tumor-specific T cells, including CD8+ T cells and CD4+ T cells." (PMID 40458394, 2025). "Conversely, CD300a/c− CD4+ T cells are more related to a TH17 profile, expressing IL-17A, which may promote tumor progression in certain tumor microenvironments." (PMID 40507267, 2025). "Moreover, in a B16-OVA tumor model, SPOP inhibition similarly enhances CD4+ CAR.CD19-T cell tumor infiltration, resulting in improved tumor control." (PMID 41148213, 2025). "AuLtNps exhibited a proinflammatory cytokine secretion profile with increases in CD3, CD8+ T, and CD4+ T cells, as well as an increase in the proportion of CD22+ cells, suggesting that nanoparticles obtained using tumor lysate as a reducing agent activate both humoral and cellular immunity." (PMID 40143109, 2025). "In addition, it was found that the expression of PD-1 and TIM-3 was significantly upregulated in CD4+ and CD8+ T cells isolated from tumor tissues and ascites of patients with hepatocellular carcinoma." (PMID 40861801, 2025). "While CD4+ T cells are traditionally considered helpers for cytotoxic T lymphocyte activation, they can also produce effector cytokines, such as IFN-γ, to directly mediate tumor cell killing." (PMID 41148213, 2025). "Furthermore, there was an increase in CD4+ and CD8+ T cells within tumor infiltrates, while Tregs were significantly reduced in MDSCs and draining lymph nodes." (PMID 40534850, 2025). "Neither CD8+ nor CD4+ T cell depletion affected the tumor growth in the PBS controls without vaccine." (PMID 40857404, 2025). "We found that in mice depleted of CD8 + T cells, the overexpression of sIcosl no longer promoted tumor growth, whereas the effect persisted in mice depleted of CD4 + T cells." (PMID 40708008, 2025). "Moreover, we used blocking antibodies for NK cells, CD4+ T cells, and CD8+ T cells to confirm that these immune cells are essential for the successful control of tumor recurrence by adv@Nap gel." (PMID 41045932, 2025). "Cell-based vaccines can be derived from autologous or allogeneic human cancer cell lines or tumor lysates, either loaded on dendritic cells or administered in adjuvants to promote dendritic cell activation in order to stimulate specific CD8+ and CD4+ T cell responses." (PMID 40573922, 2025). "Furthermore, the expression of MIDN in most cancers was closely related to CD4+ and CD8+ T cells, suggesting its potential regulatory role in tumour immunity." (PMID 40111059, 2025).
tumor (continued). "Furthermore, in a study on tumor lung metastasis, CD25+B220+CD19+ B cells were found to interact with CD4+ T cells and secrete TGF-β, inducing the conversion of CD4+ T cells into FoxP3-expressing Tregs and thereby promoting lung metastasis." (PMID 41285707, 2025). "Mechanism of action experiments that designed to find an immunological explanation of RIT and immunotherapy revealed expansion of CD4+CD8+ double positive T cells, anti-tumor M1 macrophages, 4-1BB+ effector CD8+T cells and NK cells after administration of 225Ac-anti-CCR8 RIT." (PMID 41035646, 2025). "Tumor type segregation of correlation analysis showed STS tumor growth correlated significantly with increased serum levels of GM-CSF, IL-2, IL-6, IL-7, IL-18 & MCP-1, whereas increased circulatory CD4+ and CD8+ T cells numbers correlated with STS tumor regression with CPMV treatment." (PMID 40386779, 2025). "Compared to naïve mBMDNs, HCC exosome-reprogrammed mBMDNs significantly promoted the formation of tumor nodules, increased the expression of PD-1 and Tim3, and reduced the expression of IFN-γ and TNF-α in liver-infiltrating CD8+ T cells and CD4+ T cells." (PMID 40083930, 2025). "Two months after complete tumor regressions and cessation of treatment, the proportion of CD44 + CD62L− effector memory and CD44 + CD62L + central memory CD4 + and CD8 + T cells were higher in the blood of cured mice compared to treatment-naïve mice implanted with tumors." (PMID 40585246, 2025). "In addition, CD19 CAR T cells derived from purified CD4+ or CD8+ Tcm or Tn were shown to exhibit improved metabolic adaptability and sustained anti-tumor activity." (PMID 41346587, 2025). "Seventy-one percent of patients induced both CD4+ and CD8+ mKRAS-specific T cells and the induction of both CD4+ and CD8+ T cells significantly correlated with overall tumor biomarker response, indicating the potential importance of a balanced T cell response for improved tumor biomarker response." (PMID 40790272, 2025). "Further analysis confirmed the negative correlation between the numbers of AKT+CD4+ T cells and Foxp3+CD4+ T cells in the mouse tumor tissues." (PMID 39743020, 2025). "Notably, both CD4+ and CD8+ T cells in the CTT group exhibited tremendous transcriptional alterations compared to those in the tumor-bearing group." (PMID 40277945, 2025). "Furthermore, IL-8 stimulation promoted the differentiation of PBMCs into CD4 + Tregs and M2 macrophages while decreasing the proportions of CD8 + T cells and M1 macrophages, as confirmed in vivo in multiple tumour models." (PMID 41163221, 2025). "Additionally, SiGel@SN38/aOX40 treatment resulted in the highest proportions of CD4+ and CD8+ T cells, accompanied by elevated serum and tumor levels of IFN-γ and TNF-α compared to other groups." (PMID 40176815, 2025). "Another key factor in CD4+ and CD8+ therapy is monitoring the tumour T-cell infiltration." (PMID 40906384, 2025). "PRMT2 can induce the polarization of tumor-associated macrophages (TAMs) towards the M2 phenotype (tumor-promoting, immunosuppressive) and inhibit the function of CD4+ and CD8+ T cells, leading to their exhaustion, thereby synergistically driving tumor progression and immune escape." (PMID 41154773, 2025). "About 107 of these antigen-loaded DCs are injected intradermally back into the patient where they migrate to regional lymph nodes, guided by chemokine signals, and where they present tumor antigens to both CD8+ cytotoxic T cells and by cross-presentation to CD4+ helper T cells (see Section 2.2)." (PMID 41374974, 2025). "Notably, CD4+ naïve T cells exhibited pronounced downregulation of the MAPK pathway, highlighting functional suppression in this subset during tumor progression." (PMID 41246350, 2025). "FKBP51 expression in CD4 tumor-infiltrating lymphocytes, rather than tumor cells, defines a protumor TME that supports H/RS cell survival." (PMID 41256864, 2025).